IL22 (interleukin 22)
Diseases named in the same sentence as IL22 in open-access papers (continued):
Sharing a sentence is not in itself a finding about the gene and the disease.
COVID-19 (continued). "IL-22 and IL-33 showed up-regulated serum concentrations in patients with mild/moderate COVID-19." (PMID 36875710, 2023). "IL-22 and IL-33 are among the least explored pro-inflammatory cytokines in COVID-19." (PMID 36875710, 2023). "Anti-cytokine autoantibodies (e.g., antibodies against IFNα, IFNε, IL-6, IL-22, GM-CSF and TNFα) may also provide a potential target for COVID-19 treatment." (PMID 36341384, 2022). "It is crucial to analyze further the functional role of IL-22/IL-22R1 interactions on immune cells during the recovery phase from COVID-19, as it could shift from a beneficial to a detrimental response over time." (PMID 35422799, 2022). "In addition, in the case of people with a severe course of COVID-19, a greater Th17 response and related interleukin-17 (IL-17), interleukin-21 (IL-21), interleukin-22 (IL-22) and granulocyte-macrophage colony-stimulating factor (GM-CSF) were also noted." (PMID 36294388, 2022). "IL-22-producing CD56dim NK cells, a subset with a relatively stable number of cells in COVID-19 patients, were positively correlated with the numbers of IL-22R1+ non-classical monocytes, the subset of IL-22R1+ monocytes with the highest rise in severe COVID-19 patients." (PMID 35422799, 2022). "For example, TREM1 Signalling (z-score = 3.157; BH p-value = 3.162 × 10–02), STAT3 Pathway (z-score = 0.949; BH p-value = 7.762 × 10–03) and IL-22 signalling (z-score = 1.732; BH p-value = 2.239 × 10–02) were all amongst the pathways upregulated in severe COVID-19 compared to mild COVID-19." (PMID 35844004, 2022). "In contrast, the association between the increase of Tc17 cells and the severity of COVID-19 may reveal the destructive effect of co-expression of IL-17 and IL-22." (PMID 35967401, 2022). "Similar to Adv5, it can be postulated that the fibrotic process observed in the SG in the context of the COVID-19 may also be dependent on the presence of IL-22, given the evidence that the Th17 pathway is hyperactivated during the course of infection with the SARS-CoV-2 virus." (PMID 39469708, 2024). "As COVID-19 is a respiratory disorder with similar pathological features and symptoms comparable to other severe pulmonary virus infections, it is reasonable to speculate that IL-22 may also serve to limit the severity of this illness." (PMID 39258622, 2024). "Further research is needed to elucidate the specific mechanisms and functions of IL-22 in regulating the pulmonary microenvironment and its involvement in pro-inflammatory processes before it may be used as a new immunotherapeutic strategy for COVID-19." (PMID 39258622, 2024). "In contrast, the association between increased Tc17 cells and COVID-19 severity may reflect the negative impact of IL-17 and IL-22 coexpression." (PMID 39258622, 2024). "Therefore, IL-22/Th22 cells may play a critical role in the pathological process of COVID-19, but the detailed mechanism still awaits further research." (PMID 36839448, 2023). "Therefore, exploring IL-22 and IL-33 in COVID-19 and their relationship to each other may expand our understanding of the pathogenic mechanism associated with the disease." (PMID 36875710, 2023). "As COVID-19 is a respiratory disorder with similar pathological characteristics and symptoms to other serious pulmonary virus infections, it is reasonable to speculate that IL-22 may also serve to limit the severity of this disease." (PMID 35967401, 2022). "In addition, high numbers of different subsets of IL-22R1 expressing myeloid cells were correlated with the plasma concentrations of various immune mediators described as important in the pathogenesis of SARS-CoV-2 infection, strengthening the potential importance of IL-22/IL-22R1 axis in COVID-19." (PMID 35422799, 2022). "PLWH with COVID-19 with a detectable VL had significantly lower concentrations of IL-2, IL-4, IFN-γ, IL-20, IL-22, IL-35, and IL-12p40 than PLWH with COVID-19 with an undetectable VL." (PMID 39597537, 2024).
COVID-19 (continued). "Whereas no significant or very low percentages of ex vivo IL-22 or IL-17A-containing T lymphocytes were observed in healthy controls, IL-22+ and IL-17A+ single positive CD4+ and IL-17A+ CD8+ T cells were detected in COVID-19 patients." (PMID 35422799, 2022). "A correlation matrix for IL-22R+ expressing myeloid cell subsets with the ex vivo IL-22, IL-17A, IFN-γ, granzyme B and perforin expressions on NK and T cells was generated to evaluate a possible relationship between these parameters in COVID-19 patients." (PMID 35422799, 2022). "Another common point of similarity in the pathogenesis of COVID-19 and SLE is interleukin-22 (IL-22), which plays a key role in the regulation of antiapoptotic proteins, influencing serum amyloid A (SAA) levels and fibrinogen production." (PMID 36431053, 2022). "In contrast, IL-22 and IFN-γ responses of NK cells to in vitro stimulation were reduced in most COVID-19 patients compared to controls." (PMID 35422799, 2022). "Longitudinal analysis of immune profiling of COVID-19 finds elevated plasma levels of IL-17A and IL-22 along with increased IL-17 secretion by CD4+ T cells in severe patients, indicative of promotive effects of Th17 cells in COVID-19 progression." (PMID 33584679, 2020). "Antigen-specific production of cytokines related to a Th17 response was also consistently detected; PBMC from COVID-19 ARDS patients produced significantly more IL-17A, IL-17F and IL-22 than HC." (PMID 32591408, 2020). "Th17 cells from approximately 50% of individuals with PCC had no capacity to express IL-17A and IL-22, similar to individuals with critical COVID-19, which would prevent clearing extracellular pathogens." (PMID 39257580, 2024). "IL-22 has not been well explored in the immunopathogenesis of COVID-19 as few studies have been conducted in this context." (PMID 36875710, 2023). "Most previous studies were concerned with examining systemic concentrations of IL-22 and IL-33 in patients with severe/critical COVID-19, while data for mild/moderate cases are not overwhelming." (PMID 36875710, 2023). "According to previous studies, IL-22/Th22 is protective against influenza and RSV pneumonia and may exert a similar effect against COVID-19." (PMID 36839448, 2023). "During the first wave of the pandemic, we characterized the IL-22/IL-22R axis at different time points in peripheral blood cells from COVID-19 patients presenting non-severe or severe forms and receiving no other treatment than a supportive one." (PMID 35422799, 2022). "The frequencies of IL-22+ CD56bright and CD56dim NK cells detected in the absence of in vitro stimulation were higher in COVID-19 patients than controls." (PMID 35422799, 2022). "The ratios of the serum concentrations of IL-22 and sCD30 were enhanced in the survivors with respect to the non-surviving severe COVID-19 patients." (PMID 36142255, 2022). "We investigated the circulating levels of IFNγ, IL-4, sIL-4R, IL-5, IL-9, IL-17A, IL-17F, IL17-E/25, IL-22 and sCD30 in surviving and non-surviving severe COVID-19 patients and healthy controls." (PMID 36142255, 2022). "As COVID-19 is a respiratory disease that shares some symptoms with influenza, it is possible that ILC3 production of IL-17 and IL-22 also may serve to limit disease severity." (PMID 33968082, 2021). "For instance, it becomes evident that, adult COVID-19 patients show a rise, in the numbers of Tc22 and Th22 cells that express IL-22 compared to healthy individuals, irrespective of the disease manifestation as asymptomatic pneumonia, mild pneumonia, or severe pneumonia." (PMID 38216935, 2024). "In addition, Th17 cells from more than 50% of individuals with PCC showed no capacity to express cytokines such as IL-17A and IL-22, similar to participants with critical COVID-19." (PMID 39257580, 2024). "Therefore, the current study aimed to analyze serum IL-22 and IL-33 concentrations in non-hospitalized patients exposed to mild/moderate COVID-19." (PMID 36875710, 2023).
COVID-19 (continued). "However, COVID-19 patients with different prognoses have similar IL-22 levels, suggesting that IL-22 does not affect the outcomes of SARS-CoV-2 infection." (PMID 36839448, 2023). "IL-22 was detectable neither in plasmas of COVID-19 patients nor in healthy controls." (PMID 35422799, 2022). "Mechanically, IL-22 has been reported to be robustly expressed by SARS-CoV-2-specific CD4+ T cells, and IL-22 is closely related to tissue repair, especially in lung epithelial cells, suggesting that SARS-CoV-2 CD4+ T cell response may play an active role in lung tissue repair during COVID-19." (PMID 37601070, 2023). "Specifically, we compared the levels of IFN-γ, IL-6, IL-22, IL-4, IL-8, IL-10, and IL-17A between anti-SARS-CoV-2 IgG-positive and seronegative individuals, all without a history of COVID-19." (PMID 40160814, 2025). "Accordingly, anti-cytokine aAbs (e.g., antibodies against IFN-α, IFN-ε, IL-6, IL-22, GM-CSF, and TNF-α) were proposed for COVID-19 and non-COVID-19 treatment, although with different results, since some improved clinical outcomes, while others had no benefit." (PMID 37243300, 2023). "Nevertheless, in the COVID-19 era the role of cytokines and interferons on epithelial integrity and systemic reaction is still not clear, and IL-22 and IFN-λ might be considered as further promising targets to maintain the COVID-19 lungs' integrity, but more evidences are urgently needed." (PMID 34150807, 2021).
Insulin resistance (51 papers, 2011 to 2025). Increased resistance towards insulin, that is, diminished effectiveness of insulin in reducing blood glucose levels. "In addition, IL-22 has been implicated in hepatic inflammation, which is commonly associated with insulin resistance and non-alcoholic fatty liver disease (NAFLD)—conditions that frequently co-occur with T2DM." (PMID 41357227, 2025). "The possible mechanism by which IL-22 regulates insulin resistance and ovarian dysfunction associated with PCOS may be related to the suppression of inflammation following BA administration." (PMID 41377049, 2025). "Studies showed that the common Bacteroides in intestinal microorganisms of PCOS patients increased significantly, which may be caused by the reduction of IL-22, insulin resistance and finally PCOS by affecting the level of bile acid synthesis." (PMID 36909735, 2023). "Supporting the observation of insulin resistance in KO mice, we found higher expression of inflammatory cytokines, including TNFα, IFNγ, IL-1β, IL-6 and IL-22, in the muscles of KO mice fed with normal diet, compared to the control mice." (PMID 41234234, 2025). "In PCOS studies, troxerutin troxerutin has been shown to attenuate dihydrotestosterone-induced insulin resistance in rats by inhibiting IL-22/JAK1/STAT3 signaling activation." (PMID 41573199, 2025). "The indirubin, an AhR agonist, induced the secretion of IL-10 and IL-22 by activating AhR to prevent high-fat diet-induced insulin resistance in mice model." (PMID 39944639, 2025). "This review elucidates the role of GM in the pathogenesis and metabolic disorders of PCOS, encompassing insulin resistance (IR), hormonal imbalances, bile acid metabolic disorders, Interleukin-22-mediated immune dysregulation, and brain-gut axis disturbances." (PMID 40357203, 2025). "The cytokines they secrete, such as IL-17A and IL-22, promote insulin resistance and adipose tissue inflammation." (PMID 41427046, 2025). "Reduced IL-22 levels in PCOS individuals, while IL-22 administration improves insulin resistance, menstrual cycle disorders, and ovarian morphological abnormalities, making it a potential treatment for PCOS with hyperandrogenism phenotypes." (PMID 41377049, 2025). "IL-17 and IL-22, two major effector cytokines primarily produced by Th17 and Th22 cells, have also been shown to be involved in insulin resistance." (PMID 41357227, 2025). "An example of this would be B. vulgatus introduced into recipient mice led to decrease IL-22 secretion, which correlated with disruption in uterine function, insulin resistance, and altered bile acid metabolism." (PMID 39229279, 2024). "Previous research has shown that interleukin-22 (IL-22) can suppress β-cell stress, reduce local islet inflammation, restore appropriate insulin production, reverse hyperglycemia, and ameliorate insulin resistance in preclinical models of diabetes." (PMID 38811532, 2024). "Interleukin-22 (IL-22) is a novel cytokine of the IL-10 family, which has shown evidence in recent studies to alleviate metabolic syndrome in obese mice, improve insulin resistance, and regulate the expression of genes related to lipogenesis." (PMID 39166109, 2024). "In our previous study, IL-22 is previously known to promote browning of white adipose tissue and improve insulin resistance in PCOS." (PMID 38734641, 2024). "Regardless, due to the extensive chronic low-grade inflammatory response in PCOS, IL-22 has been reported by many studies to alleviate PCOS by improving systemic inflammation levels as well as insulin resistance." (PMID 38734641, 2024). "WG significantly improved markers of insulin resistance and upregulated jejunal Il10 and Il22 genes." (PMID 37181127, 2023). "Transplanted fecal microbiota from PCOS-afflicted women or Bacteroides vulgatus into recipient mice resulted in infertility, insulin resistance, altered bile acid metabolism, decreased interleukin 22 (IL-22) production, and ovarian dysfunction." (PMID 37140372, 2023).
Insulin resistance (continued). "IL-22 has been reported to effectively improve insulin resistance and lipid metabolism disorders in the therapy of DN." (PMID 36544775, 2022). "Mice transplanted with stool from PCOS patients display a reduced percentage of IL-22+ ILC3s and develop insulin resistance." (PMID 35574038, 2022). "Previous studies have reported the efficacy of IL-22 to regulate glucose metabolism by improving insulin resistance." (PMID 36544775, 2022). "IL-22 and IL-17 production is suggested to induce inflammatory responses and lead to insulin resistance by activating JNK signaling in insulin-targeting hepatocytes, which was proven to correlate with hepatic lipid accumulation and steatohepatitis." (PMID 34944732, 2021). "IL-22 is known to play an important role in maintaining glucose homeostasis and insulin resistance and restores the mucosal host defense by bacterial clearance in various bacterial infections." (PMID 31809521, 2019). "Mice studies show gut barrier disruption and diet-induced insulin resistance can be alleviated by cytokine interleukin-22 (IL-22)." (PMID 30978932, 2019). "Other studies have challenged the notion that IL-22 ameliorates insulin resistance and chronic inflammation in mice or humans." (PMID 28143481, 2017). "Furthermore, recombinant IL-22 can reverse glucose intolerance, hyperglycemia, and insulin resistance in obese mice." (PMID 40243151, 2025). "This potential synergy could contribute to IL - 17A/IL-22 releases, which may further exacerbate insulin resistance and systemic inflammation." (PMID 40969555, 2025). "In addition, IL-22 plays an important role in alleviating the metabolic syndrome by improving insulin resistance." (PMID 38734641, 2024). "In patients with metabolic disorders, an important gut finding is a decrease in tryptophan, which leads to a decrease in aryl hydrocarbon receptor binding and the activation of both GLP-1 and interleukin-22; this pathway ultimately promotes inflammation, insulin resistance, and hepatic steatosis." (PMID 38375198, 2024). "Furthermore, the GTT and ITT results showed that insulin resistance in PCOS mice was significantly alleviated by IL-22, and the AUC of the GTT results were decreased by IL-22." (PMID 38734641, 2024). "Animal studies have shown that supplementation with interleukin-22 (IL-22) or glycodeoxycholic acid (GDCA) ameliorates insulin resistance in B. vulgatus mice and significantly corrects estrous cycle dysfunction, alters ovarian morphology, and improves abnormal hormone levels." (PMID 36836035, 2023). "It is suggested that the mechanism of IL-22 improving PCOS insulin resistance and ovarian function may be related to inhibiting the inflammatory response of ovarian granulosa cells." (PMID 36909735, 2023). "In addition, as IL-22 produced by intestinal group 3 innate lymphoid cells (ILC3) reversed insulin resistance, interactions among the gut microbiota, bile acid, and IL-22 appear to have roles in the pathophysiology of PCOS." (PMID 36798125, 2023). "We have found that IL-22 could also alleviate the abnormal lipid metabolism, reduce lipotoxicity in renal cells, attenuate insulin resistance, and ultimately improve the prognosis of DN." (PMID 36544775, 2022). "With the use of a PCOS-like murine model, it was shown that treatment with more IL-22 could lead to a full recovery of ovarian morphology, reproductive cycles, and insulin resistance." (PMID 36091010, 2022). "Glycodeoxycholic acid induces intestinal ILC3s to secrete IL-22, improving insulin resistance." (PMID 35574038, 2022). "Interestingly, defective intestinal production of IL-22 was observed in mice fed a high-fat diet, while administration of exogenous IL-22 reversed many metabolic symptoms, including hyperglycaemia and insulin resistance." (PMID 32487227, 2020).